WIF1 (Wnt inhibitory factor 1)
Diseases named in the same sentence as WIF1 in open-access papers (continued):
Sharing a sentence is not in itself a finding about the gene and the disease.
glioma (6 papers, 2016 to 2024). A benign or malignant brain and spinal cord tumor that arises from glial cells (astrocytes, oligodendrocytes, ependymal cells). "HOXC6 was found to be overexpressed in clinical glioma samples, and its knockdown stimulated the WIF-1/Wnt signaling pathway and induced cell cycle arrest and apoptosis in U87 glioma cells." (PMID 38499392, 2024). "Interestingly, in vivo studies demonstrated that upregulated HOXC6 could inhibit the Wnt inhibitory factor-1 (WIF-1) expression and activate Wnt signaling pathway in glioma cells." (PMID 34617205, 2022). "Based on our data, CBX7 should be added to this growing list of β-catenin regulators in glioma that includes SFRP1, DKK1 and Wif1." (PMID 28388562, 2017). "Dysregulation of the Wnt canonical pathway leading to beta-catenin activation has been detected in glioma patients with overexpression of WNT3a and epigenetic-driven downregulation of inhibitors like SFRP1, Dkk1 or Wif1." (PMID 27613837, 2016).
Arthritis (5 papers, 2015 to 2022). Inflammation of a joint. "Moreover, WIF-1 is shown to have a protective effect against cartilage degradation in experimental arthritis, and has important effects in promoting the balance of cartilage and bone turnover." (PMID 32650720, 2020). "It promotes arthritis progression via miR-17-5p/FUT2/β-catenin axis, and cartilage degradation in osteoarthritis by inhibiting WIF-1 expression and activating the Wnt pathway." (PMID 35626352, 2022). "Another antagonist, Wnt inhibitory factor 1 (WIF1), expressed in chondrocytes, is downregulated in experimental arthritis and articular cartilage of RA patients." (PMID 33990546, 2021).
melanoma (5 papers, 2013 to 2024). A malignant, usually aggressive tumor composed of atypical, neoplastic melanocytes. "Aberrant expression of WNT/β-catenin antagonists (e.g., DKKs, WIF1, sFRPs) is common in melanoma and is associated with elevated β-catenin level." (PMID 32659938, 2020). "Reduced level of WIF1 has been found to contribute to constitutive activation of canonical WNT-signaling in melanoma cells, and WIF1 overexpression resulted in downregulation of WNT-signaling and suppression of melanoma cell proliferation." (PMID 32659938, 2020). "Forced expression of DKK1 or WIF-1 reduces melanoma cell growth and activates cell death." (PMID 24416617, 2013). "Additionally, expression of negative regulators of canonical Wnt signaling pathway such as Dickkopf-1, 2, 3 (Dkk-1, 2, 3) and Wnt inhibitory factor-1 (WIF-1) is strongly reduced or lost, both in melanoma cell lines and tumor samples." (PMID 24416617, 2013). "Melanoma CAF subpopulations usually include iCAFs and myCAFs, however, a number of other unique clusters have been put forth including, distinct ECM and contractile CAFs in, Wif1 and Zeb2 subpopulations, and matrix and RGS5." (PMID 38525245, 2024).
osteoporosis (5 papers, 2019 to 2025). A condition of reduced bone mass, with decreased cortical thickness and a decrease in the number and size of the trabeculae of cancellous bone (but normal chemical composition), resulting in increased fracture incidence. "The levels of miR-424-5p and WIF1 were testified by qRT-PCR, which confirmed that miR-424-5p was overexpressed, while WIF1 was knocked down in exosomes from osteoporosis patients." (PMID 34229300, 2021). "Hypermethylation of CpG islands of bone-inhibitory factors, like SOST, dickkopf-1 (DKK1), and Wnt inhibitory factor 1 (WIF1) are present in postmenopausal women with osteoporosis." (PMID 32664681, 2020). "It is therefore conclusive that gossypol protected against osteoporosis via inhibiting the expression of WIF1." (PMID 31139657, 2019). "As a consequence, the gossypol-mediated protection against osteoporosis was significantly blunted after overexpression of WIF1 through a genetic approach." (PMID 31139657, 2019). "WIF1 could therefore serve as a key target in the research and development of therapies for osteoporosis." (PMID 39606935, 2025). "Moreover, overexpressing WIF1 inhibits the miR-424-5p expression in osteoblast differentiated cells, while BMSCs-derived exosomes partially reverses the osteogenic effect of BMSCs-derived exosomes in osteoporosis patients through WIF1 overexpression." (PMID 34229300, 2021). "SFRP and WIF1 can directly interact with Wnt ligands, blocking the binding of the ligands to the receptor and inactivating the Wnt signaling pathway by regulating the transcription of downstream target genes, ultimately leading to the occurrence and progression of osteoporosis." (PMID 39606935, 2025). "Then, we adopted western blot to determine the WIF1/Wnt/β-catenin protein expression, and discovered that compared with that in exosomes extracted from normal cells, WIF1 was knocked down, while Wnt and β-catenin were overexpressed in exosomes from osteoporosis patients." (PMID 34229300, 2021). "Specifically, inhibitors of the Wnt signaling pathway, including sclerostin, DKK1, WIF1, and SFRP, negatively regulate bone formation during osteoporosis." (PMID 39606935, 2025). "Accordingly, inhibitors of this pathway, such as sclerostin, Dickkopf-1 (DKK1), WNT inhibitory factor 1 (WIF1), and secreted frizzled-related proteins (SFRPs), have a negative regulatory role in bone formation and may serve as effective therapeutic targets for osteoporosis." (PMID 39606935, 2025). "Thus, targeting Wnt signaling pathway inhibitors, such as sclerostin, DKK1, WIF1, and SFRP, to regulate the expression of key molecules in the Wnt pathway represents a promising and safe therapeutic strategy for osteoporosis." (PMID 39606935, 2025).
astrocytomas (4 papers, 2010 to 2024). "In summary, we provide evidence that WIF-1 is not only frequently hypermethylated in astrocytomas but this epigenetic alteration of the WIF-1 gene is associated with reduced expression." (PMID 20334650, 2010). "In this study, we demonstrated that WIF-1 downregulation or silencing was associated with aberrant methylation of promoter region in malignant astrocytoma tissue samples." (PMID 20334650, 2010). "With this work we intended to investigate the expression and promoter methylation status of WIF-1 gene in human astrocytomas." (PMID 20334650, 2010). "In this study, we analysed the protein and mRNA level of WIF-1 in astrocytomas using immunohistochemistry and RT-PCR." (PMID 20334650, 2010). "WIF-1 mRNA was examined in 6 normal brain tissues as well as in 53 resected astrocytoma tissues [Tab." (PMID 20334650, 2010). "Our results demonstrate that the WIF-1 gene is frequently down-regulated or silenced in astrocytomas by aberrant promoter methylation." (PMID 20334650, 2010). "As the pathological grade increased, the protein and mRNA expression of WIF-1 gene in astrocytoma were decreased." (PMID 20334650, 2010). "The average expression levels of WIF-1 protein and mRNA in astrocytomas were decreased significantly compared with normal control tissues." (PMID 20334650, 2010). "The protein and mRNA expression of WIF-1 gene in astrocytomas was decreased with the increase of pathological grade." (PMID 20334650, 2010). "Furthermore, WIF1 expression has been found to be downregulated in astrocytomas, with the degree of WIF1 suppression correlating with the histological grade of the tumors." (PMID 38612480, 2024). "Furthermore, WIF-1 promoter methylation was observed by MS-PCR in astrocytomas which showed significant reduction of WIF-1 expression." (PMID 20334650, 2010). "Yet little is known regarding the expression and promoter methylation of WIF-1 in astrocytomas." (PMID 20334650, 2010). "In this study, we describe for the first time that the expression of WIF-1 was frequently downregulated by its promoter hypermethylation in astrocytomas compared with normal tissue samples, which might contribute to the upregulation of Wnt/β-catenin signaling in astrocytoma carcinogenesis." (PMID 20334650, 2010).
chondrosarcoma (4 papers, 2017 to 2024). A malignant cartilaginous matrix-producing mesenchymal neoplasm arising from the bone and soft tissue. "In esophageal squamous cell carcinoma cells 43 and human chondrosarcoma cells 44, HOTAIR inhibits WIF1 expression by promoting trimethylation of H3K27 in the WIF1 promoter, thereby activating Wnt/ β-catenin pathway." (PMID 38725864, 2024).
colorectal tumor (4 papers, 2006 to 2021). "WIF1 promoter methylation analyses by ddPCR is a sufficient and sensitive tool to verify that DNA isolated from plasma derived from colorectal tumor cells." (PMID 32766143, 2020). "Interestingly, in our previous work using the same detection method, we demonstrated expected hypermethylation of WIF1 in colorectal tumour tissues, which to some extent indicated the tissue specificity of DNA methylation." (PMID 33992091, 2021). "This parallels previous data for WIF-1 and DKK-1, and infers that colorectal tumours should express high levels of all three classes of Wnt antagonists as a result of the β-catenin stabilising mutations normally present." (PMID 16523202, 2006). "In the cohort, 23 primary colorectal tumor tissues were analyzed associated with 11 adjacent non-tumor tissues to measure DNA hypermethylation of NPY and WIF1, as potential new biomarkers of CRC in liquid biopsies." (PMID 34627187, 2021).
esophageal squamous cell carcinoma (4 papers, 2020 to 2024). Esophageal squamous cell carcinoma (ESCC) is a type of esophageal carcinoma (EC) that can affect any part of the esophagus, but is usually located in the upper or middle third. "Additionally, the polycomb repressive complex 2 (PRC2) and lncRNA HOTAIR regulate WIF-1 expression by increasing H3K27 methylation in the promoter region, activating the Wnt/β-catenin signaling pathway in esophageal squamous cell carcinoma (ESCC)." (PMID 37384249, 2023).
gastric cancer (4 papers, 2016 to 2021). A primary or metastatic malignant neoplasm involving the stomach. "In nasopharyngeal cancers and gastric carcinoma cell lines the promoters of WIF1 is hypermethylated, and his expression is regulated by miR-BART19-3p." (PMID 34627187, 2021). "WIF1 and DKK3 to poor prognosis in breast cancer; FGR3 mutation and hypermethylation to bladder cancer and SFRP2 hypermethylation to gastric cancer (GC)." (PMID 27050149, 2016).
leukemia (4 papers, 2009 to 2022). A malignant (clonal) hematologic disorder, involving hematopoietic stem cells and characterized by the presence of primitive or atypical myeloid or lymphoid cells in the bone marrow and the blood. "A significant increase in miR-181a-5p was observed in multiple leukemia cell lines and acute lymphocytic leukemia samples, and miR-181a-5p activates the Wnt/β-catenin signaling pathway by inhibiting WIF1, thus promoting leukemia cell growth." (PMID 35339759, 2022).
nasopharyngeal carcinoma (4 papers, 2021 to 2023). A carcinoma arising from the nasopharyngeal epithelium. "Consistently, ectopic expression of WIF-1 in nasopharyngeal carcinoma (NPC) and ESCC cells considerably attenuates the colony formation of tumor cells accompanied with significant down-regulation of beta-catenin protein." (PMID 34488905, 2021). "In nasopharyngeal carcinoma cells, SFN inhibits growth through the DNMT1/Wnt inhibitory factor 1 (WIF1) axis, as well as inhibits total STAT3 oncogene expression level and STAT3 phosphorylation (troy 704 and troy 705) by upregulation of miRNA-124-3p." (PMID 35052539, 2021).
pituitary tumor (4 papers, 2021 to 2023). A benign or malignant neoplasm affecting the pituitary gland. "For example, expression of the Wnt decoy receptors sFRP2, sFRP4, and Wif1 are downregulated in pituitary tumors by epigenetic mechanisms." (PMID 36965619, 2023). "Adding to the previous data, it was demonstrated the Wnt inhibitory factor 1 (WIF1) was significantly reduced in the pituitary tumors by the increased methylation of the WIF1 promoter." (PMID 37109772, 2023). "In previous studies, the expression of the Wnt inhibitory factor 1 (WIF1) gene, which encodes an inhibitor of the Wnt signaling pathway, has been found to be significantly reduced in pituitary tumors compared to normal pituitary gland specimens due to the hypermethylation of its promoter." (PMID 34564317, 2021). "Additionally, Wnt pathway inhibitor WIF-1 was found underexpressed in human bromocriptine-resistant prolactinomas as well as in non-functioning pituitary tumors." (PMID 35928898, 2022).
asthma (3 papers, 2011 to 2022). "Among them, PDK4, FKBP5, ZBTB16, WNT5A, GMPR and WIF1 are reported to be associated with asthma in the previous researches." (PMID 36550577, 2022). "Interestingly, WIF1 is linked to intrauterine airway development and lung function impairment which make neonates prone to asthma in the future." (PMID 33791298, 2021). "PDK4 (P-value < 0.001) and ZBTB16 (P-value < 0.01) were up-regulated in asthma group, while WNT5A (P-value < 0.05), NR4A3 (P-value < 0.001) and WIF1 (P-value < 0.05) were down-regulated." (PMID 36550577, 2022). "Asthmatic patients with Wnt regulator (WIF1, WNT5B, and DKK3) enrichment were atopic, had early-onset, long duration, and had severe asthma with the inflammatory profile." (PMID 33791298, 2021). "Wnt signaling genes (e.g. Wif1, Wisp1) were not identified as asthma genes in our literature search, and were thus not included in our analyses." (PMID 21699702, 2011).
Barrett esophagus (3 papers, 2010 to 2019). Esophageal lesion lined with columnar metaplastic epithelium which is flat or villiform. "Epigenetic remodeling in EAC and Barrett’s esophagus has already been reported, with silencing of the Wnt inhibitory factor-1 (WIF-1) and secreted frizzled receptors." (PMID 30841855, 2019).
cardiac hypertrophy (3 papers, 2013 to 2023). "In our datasets, we identified several fibroblast subclusters reported in previous scRNA-seq study of cardiac hypertrophy induced with Angiotensin II, including fibroblast-Thbs4 and fibroblast-Wif1." (PMID 36805782, 2023). "On the basis of mouse scRNA-seq data, several subpopulations of fibroblasts, e.g., fibroblast-Thbs4, fibroblast-Wif1, fibroblast-Cd248 and fibroblast-vegfd, were found in hypertrophy heart." (PMID 36805782, 2023). "Myl7 has been shown to inhibit cardiac hypertrophy, whereas Wif1 impacts hypertrophy through inhibition of the Wnt/β-catenin pathway." (PMID 35380160, 2022). "Our results indicate that WIF1 significantly decreases the expression levels of nppb, suggesting that WIF1 regulate cardiac hypertrophy and that remodeling is in part due to interaction with nppb." (PMID 23921644, 2013). "Considered that fibroblast-Wif1 played a negative role in cardiac fibrosis development, the decreasing percentage of fibroblast-Wif1 during the progress of cardiac hypertrophy may be a reason for heart function deterioration." (PMID 36805782, 2023).
colorectal adenoma (3 papers, 2008 to 2021). An adenoma that arises from the colon or rectum. "The WIF1 gene promoter hypermethylation has been reported in circulating DNA isolated from plasma of colorectal adenoma and CRC patients." (PMID 24289328, 2013). "WIF1 binds to secreted Wnt ligands and is frequently downregulated by CGI methylation in gastrointestinal cancers, including colorectal adenomas." (PMID 18542073, 2008).
dysplasia (3 papers, 2019 to 2026). A usually neoplastic transformation of the cell, associated with altered architectural tissue patterns. "The ENDCAP-C trial, a multicenter study to assess the role of molecular markers in improving the detection of dysplasia, identified the methylation of a five-marker panel (SFRP2, SFRP4, WIF1, APC1A, APC2) that accurately detected ulcerative colitis associated dysplasia." (PMID 41562706, 2026). "For neoplastic mucosa a five marker panel (SFRP2, SFRP4, WIF1, APC1A, APC2) was accurate in detecting pre-cancerous and invasive neoplasia (AUC = 0.83; 95% CI: 0.79, 0.88), and dysplasia (AUC = 0.88; (0.84, 0.91)." (PMID 30473377, 2019).
esophageal cancer (3 papers, 2010 to 2018). A primary or metastatic malignant neoplasm involving the esophagus. "For instance, HOTAIR represses the expression of Wnt inhibitory factor 1 (WIF-1), an inhibitor of the Wnt/β-catenin pathway that mediates EMT in esophageal cancer cells." (PMID 25491133, 2014).
fibrosis (3 papers, 2016 to 2023). the formation of excess fibrous connective tissue in an organ or tissue in a reparative or reactive process. "Cluster 10 (fibroblast-Wif1) showed increased expression of genes (Wif1, Dkk3, Sfrp1, Sfrp2) involved in negative regulation of Wnt signaling pathway, which has been considered to inhibit cardiac fibrosis." (PMID 36805782, 2023). "Next, we tested whether circulating WIF1 can also protect mice against the development of fibrosis in UUO model mice." (PMID 35332151, 2022). "Given that WIF1 was predicted as a putative target of miR-17-5p, we hypothesized that miR-17-5p might promote hepatic fibrosis via inhibiting WIF1 expression." (PMID 26637809, 2016).
medulloblastoma (3 papers, 2014 to 2021). A malignant, invasive embryonal neoplasm arising from the cerebellum. "WIF1 is known to be silenced in these medulloblastoma cell lines as a result of promoter methylation." (PMID 32410663, 2020). "In accord with previous reports, we identified distinct groups of co-expressed genes that were highly enriched for WNT signalling in WNT medulloblastoma, (including DKK1, DKK2, DKK4, WIF1, LEF1 and WNT16)." (PMID 25412507, 2014).
oral cancer (3 papers, 2012 to 2017). "Promoter hypermethylation-mediated downregulation of WIF1 in oral cancers has been reported by multiple groups, so there is evidence to suggest that epigenetic alteration of this gene can contribute to invasive disease phenotypes." (PMID 22645611, 2012). "In our study, WIF1 was the most frequently methylated gene in oral carcinomas." (PMID 25487617, 2015). "Results so far suggest that WIF1 alterations may only have clinical utility as oral cancer biomarkers where used for diagnosis of invasive disease." (PMID 22645611, 2012). "The methylation of WIF1 may be considered a prognostic marker in oral cancers." (PMID 25487617, 2015). "Importantly, the methylation of WIF-1 correlated with shorter survival in oral cancer patients." (PMID 25487617, 2015). "In oral cancer, several genes related to WNT signaling are found silenced by DNA methylation, including SFRP (Secreted frizzled-related protein), SOX17 (SRY-box 17), and WIF1 (WNT inhibitory factor 1)." (PMID 28704968, 2017).
psoriasis (3 papers, 2020 to 2024). An autoimmune condition characterized by red, well-delineated plaques with silvery scales that are usually on the extensor surfaces and scalp. "In as early as 2010, it was indicated that altered Wnt signaling played an important role in psoriasis, as Wnt-5a was upregulated in psoriatic lesions, whereas WIF-1 was downregulated." (PMID 38008779, 2023). "We speculate that wif-1 plays a vital role in the pathogenesis of psoriasis." (PMID 32795328, 2020). "By intersecting the differential genes identified in all four datasets, we identified 15 common genes that exhibited high expression in both BC and psoriasis, with the exception of INA, WIF1, and TIMP4." (PMID 38605947, 2024). "However, the methylation status of wif-1 in psoriasis is unknown." (PMID 32795328, 2020).
acute lymphoblastic leukemia (2 papers, 2022 to 2025). Leukemia with an acute onset, characterized by the presence of lymphoblasts in the bone marrow and the peripheral blood. "The mature miR-181a-5p activates Wnt/β-catenin signaling by targeting Wnt inhibitory factor 1 (WIF1) in acute lymphoblastic leukemia (ALL) cells." (PMID 41189817, 2025).